IL6 (interleukin 6)
Diseases named in the same sentence as IL6 in open-access papers (continued):
Sharing a sentence is not in itself a finding about the gene and the disease.
COVID-19 (continued). "The magnitude of senescence led to a high surge of IL6, IL1b, IFNγ, C-reactive protein, and TNFα is reported in several epidemiological studies to lower airway and lung injury and risk for in COVID-19 elderly patients." (PMID 33815889, 2021). "Various studies have suggested that higher levels of inflammatory markers such as WBC, CRP, PCT, ESR, IL-6, andIL-10 are associated with the severity of COVID-19." (PMID 35539890, 2021). "In the unadjusted model, elevated serum IL-6 levels were significantly associated with a higher risk of severe COVID-19 in both groups of patients." (PMID 33763027, 2021). "Mainly, high serum IL-6 levels are considered to be associated with higher disease severity; IL-6 inhibitors, such as tocilizumab, have been used to treat severe COVID-19 patients." (PMID 34682731, 2021). "Among several cytokines, serum levels of interleukin-6 (IL-6) were associated with severity of the clinical manifestations and poor outcome of COVID-19 patients." (PMID 34704175, 2021). "High ferritin and IL-6 levels were linked to poor clinical outcomes in a multicenter retrospective investigation of 150 COVID-19 patients." (PMID 34835248, 2021). "ACE2 expression plays a key role in susceptibility to COVID-19 and is involved in innate and adaptive immune responses, affecting the immune regulation of B cells and cytokine secretion (e.g., IL-1, IL-10, IL-6)." (PMID 33815131, 2021). "Tocilizumab is a humanized monoclonal antibody against both the soluble and membrane-bound interleukin-6 receptor and therefore useful when IL6 is high as part of the COVID-19-associated cytokine storm." (PMID 34364393, 2021). "Collectively, these findings are consistent with the elevated plasma levels of inflammatory markers observed in COVID-19 patients, where the profile of IL-6, CCL2/MCP-1, and CXCL10/IP-10 are associated with the severity of the disease." (PMID 34572407, 2021). "Researchers recommended severe COVID-19 should be considered as a risk factor for invasive fungal infections, particularly those who receive immunosuppressive medications like steroids and IL-6 inhibitors (tocilizumab)." (PMID 34036149, 2021). "In patients with COVID-19, IL-6 levels are significantly elevated and associated with adverse clinical outcomes." (PMID 33920604, 2021). "Some studies have also shown that cytokine storms, such as elevated levels of interleukin-6, interleukin-7, and granulocyte-macrophage cloning replicator, are associated with more severe forms of COVID-19 in people with hypertension." (PMID 34676114, 2021). "COVID-19 patients have higher levels of plasma cytokines,interleukin family (IL-2, IL-6, IL-7, IL-10) and are at high risk for CSS." (PMID 34812049, 2021). "Our results also illustrated that the serum levels of IL-1β, TNFα, IL-6, IL-12, IL-23, and IL-33 are risk factors associated with COVID-19 severity." (PMID 34917631, 2021). "This cytokine-storm-like response in COVID-19 was supported by early reports demonstrating COVID-19 severity was associated with increased plasma levels of cytokines such as IL-6." (PMID 33959727, 2021). "Further study with a larger sample size must be conducted to obtain conclusive evidence of the association between IL-6 polymorphisms and IL-6 production and disease severity in Asian COVID-19 patients." (PMID 34634929, 2021). "Baricitinib inhibits the intracellular signaling pathway of cytokines implicated in severe COVID-19, including IL-2, IL-6, IL-10, IFN-γ, and granulocyte-macrophage colony-stimulating factor (GM-CSF)." (PMID 34063964, 2021). "Numerous clinical studies show an association of elevated IL-6 levels with the severity of COVID-19, which is consistent with our results." (PMID 34956420, 2021). "These cells, populated in the late memory fraction (IgD− CD27−, also known as double-negative B cells), release inflammatory molecules like TNF-α, IL-8, and IL-6, have been linked to autoimmune illness, chronic viral disease, and COVID-19." (PMID 35822018, 2021).
COVID-19 (continued). "In our study, male sex, severe cognitive impairment, underlying heart disease, anemia, and high plasma levels of IL-6 were independently associated with greater mortality during hospitalization in older patients infected with COVID-19." (PMID 34682421, 2021). "According to Ulhaq and Soraya (2020), there is evidence that the circulating IL-6 levels are intricately linked to the severity of infection in patients with COVID-19, especially in those with lung injury." (PMID 33791232, 2021). "The main cause of COVID-19 severity is the cytokinestorm which is associated with increasing serum levels ofinterleukin-6 (IL-6), IL-7, IL-8 and tumor necrosis factoralpha (TNF-α)." (PMID 34455712, 2021). "Several observational and in vitro studies have shown that IL-6 is a crucial cytokine associated with the severity of COVID-19 and mortality." (PMID 34959657, 2021). "Generally, severe cases of COVID-19 are associated with excessive cytokine release, with large amounts of IL-6, IL-1β, IL-2, IFN-γ, TNF-α, and other cytokines released." (PMID 34566657, 2021). "Synergistic cooperation between interferon (IFN)-gamma-induced T cell immune response and interleukin (IL)-6-induced macrophage activation in COVID-19 has been implicated in the development of ARDS." (PMID 34379684, 2021). "IL-6 concentrations observed in COVID-19 patients are well below the levels expected to cause trans-signaling and are unlikely to contribute to any remote organ pathology." (PMID 33921604, 2021). "Patients with MAFLD and elevated serum IL-6 levels at admission are at higher risk for severe illness from COVID-19." (PMID 33763027, 2021). "Decreased levels of these three T-lymphocyte subsets along with IL-6 and IL-10 were reported to be independent risk factors (OR ranging from 1.78 to 5.63) in COVID-19 patients with severe hepatic injury." (PMID 34287285, 2021). "This study confirmed that high IL-6 was associated with the poor prognosis of patients with COVID-19." (PMID 34970527, 2021). "Since elevated interleukin-6 (IL-6) levels are associated with severe disease course and mortality in COVID-19, IL-6 is suggested to be an important cytokine in SARS-CoV-2 infection pathogenesis and ‘cytokine storm’." (PMID 34016096, 2021). "Our study confirmed the relevance of NLR and IL-6 as prominent biomarkers associated with the disease severity in COVID-19." (PMID 33584733, 2021). "Up-regulation of IL-6 signaling has been observed in nasopharyngeal swab, lung and has been associated with poor outcome of COVID-19." (PMID 34775962, 2021). "The present study determined the influence of IL-6 polymorphisms on the severity of COVID-19 in Chinese patients." (PMID 34634929, 2021). "Two studies suggest that COVID-19 patients with a serum IL-6 >80 pg/ml are at high risk of respiratory failure and death." (PMID 34567235, 2021). "Severe and fatal cases of COVID-19 are often associated with increased proinflammatory cytokine levels including interleukin 6 (IL-6) and acute respiratory distress syndrome." (PMID 34835296, 2021). "Targeting the IL-1 family, anakinra has been found to downregulate CRP and IL-6 and is associated with significant survival improvement in severe COVID-19." (PMID 34205487, 2021). "The increase in IL-6 observed in severe COVID-19 patients is associated with significantly lower survival rates." (PMID 33927728, 2021). "It is conceivable that individuals with the low-producing variant genotype would avoid the prolonged and uncontrolled IL-6 synthesis in the disease progression of COVID-19." (PMID 34634929, 2021). "COVID-19 pathophysiology is associated with aggressive pro-inflammatory responses (including IL-6, IL-1β, IP-10, macrophage inflammatory protein 1α (MIP1α), MIP1β and MCP1) and airway damage." (PMID 33664772, 2021). "Recent reports indicate that the initiation and progress of the sickness caused by COVID-19 are driven by cytokine (e.g., IL-6 and IL-8) responses." (PMID 35083244, 2021).
COVID-19 (continued). "These included MCP1, IL-6, IL-1β and TNFα, which are typical components of the cytokine storm associated with respiratory failure and high mortality in COVID-19 patients." (PMID 34807265, 2021). "IL-6 production by intermediate monocytes in COVID-19 has been described in association with cytokine storm and severe disease, and in general, increased IL-6 levels correlate with disease severity." (PMID 35593707, 2021). "It is important to note that our putative biomarkers of disease progression in COVID-19 (IL6, CKAP4, Gal-9, IL-1ra, LILRB4 and PD-L1) were associated to NfL but to a much lesser extent to GFAP and tau." (PMID 33737684, 2021). "It showed that the use of IL-6 antagonists was associated with improved survival in COVID-19 patients, but the results were statistically significant only for TCZ (OR for mortality equal to 0.83; 95% CI: 0.74–0.92)." (PMID 34768455, 2021). "Low expression of human leukocyte antigen–DR isotype and lymphopenia are defined by IL-6-mediated immune dysregulation in severe COVID-19, which is associated with continuous cytokine production and hyper-inflammation." (PMID 34944639, 2021). "In fact, the overproduction of pro-inflammatory cytokines like IL-6 is associated with autoimmune disorder, and lead to cytokine storm, what is reported in severe COVID-19 patients." (PMID 34895167, 2021). "Other risk factors for AKI in COVID-19 patients include diabetes mellitus, hypertension, male gender, the need for ventilation support, and high interleukin-6 levels." (PMID 34884225, 2021). "H1N1-enriched bacteria has shown a positive association with inflammatory cytokines IL-2, IL-4, and IL-6, the later being the predominant culprit behind the onset of cytokine storm in COVID-19." (PMID 33791231, 2021). "TNFα and IFNγ are known to particularly drive COVID-19 disease severity and in addition, IL-6, IL-1β and IL-12 have been consistently implicated in severe disease." (PMID 33813138, 2021). "This is in contrast to the findings of a study which showed a positive correlation between IL-6 level and fibrinogen level in patients with COVID-19 associated ARDS." (PMID 34103044, 2021). "Recent clinical reports have shown that inflammation was induced in COVID-19 cases, and this induction was associated with an increased level of cytokines, including interleukins (IL-1β, IL-6, IL-10) and tumor necrosis factor-α (TNF-α)." (PMID 34901061, 2021). "The concentration of circulating IL-6 was closely associated with the severity of COVID-19 symptoms, the impairment of immune cell cytotoxicity and the global T cell lymphopenia." (PMID 33912590, 2021). "Further studies are needed to confirm that elevated IL-6 at admission is a risk-predictor biomarker for ICU-AW developing in COVID-19, in order to foster prevention of this complication." (PMID 33755815, 2021). "We found that vitamin D deficiency, high level of IL-6 and low level of eGFR were highly indicative in the COVID-19 tropism, the differences of the mean levels of vitamin D, IL-6, and eGFR obtained by comparing the three groups were statistically significant." (PMID 34576798, 2021). "Some studies have indicated that CRS caused by IL-6 was common in COVID-19 patients and closely related with acute respiratory distress syndrome (ARDS)." (PMID 33146673, 2021). "There is a growing body of literature evaluating outcomes associated with IL-6 inhibition in COVID-19 patients, but in disparate patient populations." (PMID 33831046, 2021). "Our study confirms these findings and shows that both NLR and levels of IL-6 were associated with severity and survival of COVID-19." (PMID 33584733, 2021). "Previous studies have identified biomarkers that significantly document a high risk of progression to severe forms of COVID-19, such as interleukin-6 and D-Dimer levels." (PMID 34070021, 2021).
COVID-19 (continued). "Multiple studies have shown the impact of IL-6 in severe COVID-19 patients and lung inflammation and its association with immune dysregulation in different states of COVID-19 sepsis." (PMID 34199761, 2021). "GM-CSF, which is rapidly produced by pathogenic Th1 cells in COVID-19, can act with other inflammatory cytokines to form a cascade signature of inflammatory monocytes with high IL-6 expression." (PMID 34054828, 2021). "The association of IL-6 levels with the severity of lung damage in both COVID-19 and other pneumonias has been shown in previous studies." (PMID 34956420, 2021). "In a prospective clinical study, we demonstrated that COVID-19 headache was associated with inflammation and the headache phenotypes were determined by several factors including elevated circulating IL-6 levels." (PMID 34384355, 2021). "The ACE polymorphism has been reported to be associated with cytokines such as IL-6, IL-8, and IL-10, which are biomarkers of severe COVID-19 patients." (PMID 35095487, 2021). "First, miR-1275 was significantly downregulated in the COVID-19 patient cohort (Log2FC = −5.48), a miRNA implicated in NF-κB IL-6 regulation." (PMID 34564316, 2021). "Tocilizumab and sarilumab, an IL-6R humanized monoclonal antibody, have been evaluated in clinical trials (NCT04330638, NCT04486521, NCT04329650) by decreasing IL6 level to decrease the risk of mortality caused by COVID-19." (PMID 34055887, 2021). "We further investigated the association between the levels of IL-6 and pulmonary injury in patients with COVID-19." (PMID 33390771, 2021). "Sarilumab, an IL-6 blocker, is currently under evaluation for its efficacy in treating pneumonia and hyper-inflammation associated with COVID-19." (PMID 34452063, 2021). "Conceivably, the combination of gp96 and IL-6, alongside thorough clinical assessment of patients, will enable more accurate stratification of high from low risk cases toward severe COVID-19." (PMID 34817280, 2021). "We identified Fcγ Receptor (FcγR) IIa and FcγRIII as the two primary IgG receptors that are responsible for the induction of key COVID-19-associated cytokines such as interleukin-6 and tumor necrosis factor." (PMID 33979301, 2021). "After adjustment for age, sex and metabolic co-morbidities, increased serum IL-6 levels remained associated with higher risk of severe COVID-19, especially among infected patients with MAFLD (adjusted-odds ratio 1.14, 95% CI 1.05–1.23; p = 0.002)." (PMID 33763027, 2021). "Obesity people is characterized by chronic inflammation and impaired innate immunity with ample production of proinflammatory factors including tumor necrosis factor (TNF-α) and interleukin-6 (IL-6), which also comprised one of risk factors for COVID-19." (PMID 34367067, 2021). "In the whole cohort of COVID-19 patients, there was a significant association between higher serum IL-6 levels and risk of having severe COVID-19 (unadjusted model: OR 1.06 [95% CI 1.03–1.09], p<0.001)." (PMID 33763027, 2021). "A large retrospective cohort study found that IL-6 levels were associated with mortality in COVID-19 patients." (PMID 37287491, 2021). "In this study, among the several inflammatory markers tested in clinical practice, sIL-2R and IL-6 were investigated for an association with mortality in COVID-19 patients with severe respiratory failure." (PMID 34575353, 2021). "Increased levels of circulating aldosterone have also been suggested to elevate IL-6 levels and this has been linked to lung injury in COVID-19." (PMID 34361021, 2021). "We aimed to assess if 25-hydroxyvitamin-D (25OHD) levels are associated with interleukin 6 (IL-6) levels and with disease severity and mortality in COVID-19." (PMID 34126960, 2021). "In conclusion, both COVID-19 and cancers were associated with lymphopenia and high levels of monocytes, neutrophils, IL-6, and IL-10." (PMID 34712741, 2021).
COVID-19 (continued). "We evaluated the association between IL-6 levels in hospitalized COVID-19 patients and 25(OH)D and dp-ucMGP as measures of vitamin D and vitamin K status, respectively." (PMID 35111793, 2021). "In the COVID-19 cohort, the systemic CCs IL6, IL1Ra, IL10, TNFa, MCP1 and IP10 had high associations with the BIMs." (PMID 34838058, 2021). "The proinflammatory cytokine IL-6 is one of the hallmark cytokines upregulated during severe COVID-19 and represents a predictive marker for the need of mechanical ventilation in accordance with CRP levels." (PMID 34659259, 2021). "Next, we assessed the anti-inflammatory impact of 4 F on SARS-CoV-2 infected cells, given prior data that 4 F attenuated release of IL-6 by influenza-infected epithelial cells and that IL-6 is associated with lung injury and severe COVID-19." (PMID 34494942, 2021). "COVID-19 and cancers were associated with lymphopenia and high levels of monocytes, neutrophils, IL-6, and IL-10." (PMID 34712741, 2021). "In a large meta-analysis of 52 manuscripts, Elshazli and coworkers found that the IL-6 level associated with COVID-19 severity was 22.9 pg/ml." (PMID 33397150, 2021). "Several of these cytokines have been implicated as mediators of COVID-19; for instance, IL-6, IL-4, IL-10 and IFNγ." (PMID 34214142, 2021). "Consistently, high levels of circulating IL-6 have been associated with the need for MV and high mortality in COVID-19 patients." (PMID 34379684, 2021). "Significantly elevated levels of IL-6 and TNF-α are correlated with COVID-19 severity, and the concentration of IL-6 in COVID-19 patients is linked to the tryptophan metabolism into the kynurenine pathway." (PMID 34803442, 2021). "This is an important finding for COVID-19 since inflammation and thrombosis, as one of the significant causes of death in COVID-19, is caused by the so-called “cytokine storm” of interleukins such as pro-inflammatory IL-6 in COVID-19 patients’ lungs." (PMID 34674775, 2021). "Elevated levels of TNFα and other pro-inflammatory cytokines and chemokines, such as IL-6, IL-10 are risk factors for the development of severe COVID-19, and their levels are much higher in critical patients than in those with milder disease." (PMID 33465050, 2021). "In the present study, IL-6 levels were also measured in sepsis patients and were 10 to 100 times higher than those in the patients with COVID-19 and were associated with prognosis." (PMID 35095877, 2021). "Life-threatening COVID-19 is associated with strong inflammation, where an IL-6-driven cytokine storm appears to be a cornerstone for enhanced pathology." (PMID 34611251, 2021). "Elevated levels of other proinflammatory cytokines like IL-1β and IL-6 in both infected lungs and plasma have been linked to COVID-19 severity." (PMID 34403366, 2021). "Prior work has also shown an association between IL-6 production and blockade of lymphopoiesis; although the extent to which this mechanism operates in COVID-19 has yet to be investigated." (PMID 33493185, 2021). "Evidence suggests that the considerable elevation of IL-6 cytokines in severe COVID-19 patients is linked to massive mucus production by stimulating the expression of the two predominant mucin genes (MUC5AC and MUC5B) in tracheobronchial epithelial cells." (PMID 34046036, 2021). "The activation and differentiation of monocytes into macrophages has been linked to the activity of IL6 and GM-CSF cytokines, which appear to play an important role in the cytokine storm of COVID-19 patients admitted to intensive care units." (PMID 34225749, 2021). "Due to their widespread use, in this paper we will be focusing specifically on the anti-IL-6/IL-6R mAbs and their use in the treatment of the COVID-19-associated cytokine storm." (PMID 34073559, 2021). "The COVID-19-associated cytokine storm is associated with elevated plasma levels of IL-6, IL-1 and TNF-α, as well as of ferritin and other inflammatory biomarkers." (PMID 34441796, 2021).